ENSG00000287190 (novel transcript)
Gene: Long non-coding RNA gene on chromosome 1 (146,044,624 to 146,052,554, reverse strand). Ensembl gene ENSG00000287190.
Gene Ontology:
Molecular function: pre-mRNA 5'-splice site binding
Biological process: mRNA 5'-splice site recognition
Cellular component: U1 snRNP